HMGA2 (high mobility group AT-hook 2)
Diseases named in the same sentence as HMGA2 in open-access papers (continued):
Sharing a sentence is not in itself a finding about the gene and the disease.
cancer (continued). "It has been suggested that HMGA2 can promote drug resistance through intrinsic resistance and induce cancer stem cell populations." (PMID 38304037, 2023). "As a proto-oncogenic chromatin regulator, HMGA2 promotes self-renewal and maintenance of cancer stem cell, and involves in different steps of tumorigenesis and malignant progression of HNSCC/OSCC." (PMID 37237385, 2023). "HMGA2 is a small AT-hook DNA binding protein that is thought to drive tumorigenesis in many types of cancers by affecting proliferation, epithelial-to-mesenchymal transition, apoptosis, DNA repair and other processes." (PMID 38058548, 2023). "LINC00355 induces chemotherapy resistance in cancer cells by regulating five downstream genes, namely HMGA2, ABCB1, ITGA2, WNT10B, and CCNE1 genes." (PMID 38125763, 2023). "This function is especially important in cells with high plasticity, such as embryonic stem cells and cancer cells, both of which display high levels of HMGA2." (PMID 36980621, 2023). "Further analysis on cancer cell-specific genes revealed that KPmut-Late tumors exhibit elevated expression levels of several genes, including Prkg2, Hmga2, Wincr1, Cdkn2a, Tnnt2, Aqp5, and Sprr1." (PMID 37998349, 2023). "Similar to the miR‐100, the miRNA let‐7 family also functions as cancer suppressor genes by inhibiting cancer cell proliferation via suppressing the expression of HMGA2, inducing apoptosis, and preventing cancer cell migration." (PMID 36545841, 2023). "Expression of HMGA2 is highest in embryonic stem cells, declines during cell differentiation and cell aging, but it is re-expressed in some cancers, where high HMGA2 expression frequently coincides with a poor prognosis." (PMID 36835656, 2023). "In the realm of cancer research, HMGA2 exhibits widespread dysregulation, playing a crucial role in nearly all malignant tumors." (PMID 38304037, 2023). "Their functional relevance for normal and neoplastic cell functions, and/or therapeutic targeting quality for the treatment of HMGA2+ cancers, continues to be the topic of ongoing studies." (PMID 36835656, 2023). "There is a body of evidence that proposes a role for HMG proteins like HMGA2 in DNA repair as well as in cancer pathogenesis and treatment." (PMID 38058548, 2023). "Previous research has reported that the high mobility group AT-hook 2 (HMGA2) is connected with many cancer developments, like differentiation and angiogenesis." (PMID 36180890, 2022). "Ectopic expression of HMGA2 has been found in various cancers including clear cell renal cell carcinoma (CCRCC), lung adenocarcinoma, colon adenocarcinoma, stomach carcinoma and others." (PMID 35439951, 2022). "Overall, our clinical data suggest that cancer-derived HMGA2 can serve as a blood-based biomarker for the prediction or diagnosis of NPC metastasis." (PMID 35388172, 2022). "Taken together, our recent study, which used various in vitro and in vivo assays, elucidated that targeting HMGA2 has a key anti-cancer role in PTC." (PMID 35213273, 2022). "For example, let-7a suppresses cancer progression by decreasing the levels of HMGA2 or RAS family members (e.g., KRAS)." (PMID 35663957, 2022). "It is evident that Hmga2 expression is increased in many different types of tumors and in some cases these tumors appear to be Hmga2 addicted, as its suppression results in a dramatic change in cancer behavior and aggressiveness." (PMID 35918713, 2022). "The expression of circ_0000658, microRNA (miR)-498, and high mobility group AT-hook 2 (HMGA2) was assessed in cancer and adjacent normal tissue collected from BCa patients and human BCa cell lines (MGH-U3, T24, 5637 and SW780)." (PMID 35031054, 2022). "Because HMGA2 plays a pivotal role in cancer metastasis progression by regulating epithelial–mesenchymal transition (EMT) in various cancers, we detected the expression of EMT target genes, such as N-cadherin, E-cadherin and vimentin by western blot analysis." (PMID 35871166, 2022).
cancer (continued). "Considering these findings, in this study, we determined the anti-cancer influences of small interfering RNA (siRNA) on the PC3 cell line by targeting HMGA2." (PMID 35620335, 2022). "The architectural transcriptional regulator high-mobility group AT-hook 2 (HMGA2) is an oncofetal protein which has been reported to be ectopically expressed in a variety of cancers." (PMID 35439951, 2022). "Hmga2 is expressed during embryogenesis; its levels are undetectable in most adult cells, while it is strongly upregulated in cancer tissues." (PMID 35918713, 2022). "HMGA2, or High Mobility Group At-hook 2, is a transcriptional modulator that plays an important role in normal cell physiology as well as cancer stem cell physiology." (PMID 35409289, 2022). "HMGA2 promotes carcinogenesis through mechanisms, such as inducing cancer cell expansion, cancer stem cell development, and apoptosis inhibition." (PMID 36313570, 2022). "Our bioinformatics analysis revealed HMGA2, an important transcription regulator with pro-oncogenic functions in various cancers." (PMID 35213273, 2022). "Functionally, elevated levels of HMGA2 protects cancer cells against DNA breaks from the topoisomerase inhibitor irinotecan." (PMID 35388973, 2022). "According to evidence, HMGA2 promotes and accelerates cancer cell proliferation through Cyclin A, Cyclin E, Cyclin D1, Cyclin B2." (PMID 35488374, 2022). "HMGA2 was also remarkably increased in PTC patient samples compared to matched non-carcinoma samples, which was negatively correlated with miR-143 expression." (PMID 35213273, 2022). "HMGA2 is regulated by the BRCA1/ZNF350/CtIP repressor complex, and miRNA-182 can prevent BRCA1 translation and increase HMGA2 expression in cancer cells." (PMID 34072941, 2021). "Here, we focus on the role of HMGA2 in the biology of TNBC and demonstrate a link between HMGA2-mediated cancer phenotypes and regulation of NF-kB/IL-6/STAT3 signaling." (PMID 34680349, 2021). "Overexpression of HMGA2 in cancer alters the cellular phenotype from epithelial to mesenchymal and also modifies cellular differentiation processes." (PMID 34680349, 2021). "Numerous studies have revealed that HMGA2 is overexpressed in many cancer cells, and overexpression of HMGA2 is correlated with progression and a poor prognosis in various malignancies, including CRC." (PMID 34844630, 2021). "Tetrac targets β-catenin and HMGA2 to promote resveratrol-induced antiproliferation in colon cancers, highlighting its potential in anti-cancer combination therapy." (PMID 34359854, 2021). "In the same way, the silencing of HMGA2 (high mobility group protein A2) has been suggested as an option in cancer treatment." (PMID 33498521, 2021). "Some reports demonstrated that HMGA2 also had a certain effect on the chemotherapeutics sensitivity of cancer cells." (PMID 34856955, 2021). "It was shown that increased HMGA2 expression in cancer supports cell proliferation by accelerating cell cycle progression." (PMID 33668453, 2021). "Further, high HMGA2 expression was associated with poor prognosis in TNBC, in agreement with our findings that HMGA2 supports several hallmarks of cancer in TNBC cells." (PMID 34680349, 2021). "We also investigated the effect of HMGA2 silencing on the cancer stem cell characteristics of MDA-MB-231 and Cal-51 TNBC cells." (PMID 34680349, 2021). "In this study, we reported that HMGA2 knockdown decreases the number of cancer colonies, as well as reduces the size of mammospheres." (PMID 33668453, 2021). "We found that the protein levels of HMGA2 in cancer cells were higher than in normal cells, especially in HeLa cells, which were used for further experiments." (PMID 34115920, 2021). "Comparing cancer to normal tissues by RNA-seq showed varying HMGA2 expression patterns in different types of cancers." (PMID 33668453, 2021).
cancer (continued). "In the current study, we proved that transferring anti-HMGA2 siRNA using MTX functionalized G4 dendrimer (G4/MTX) nanosystem lead to reduced HMGA2 gene expression and subsequently improved apoptosis mediated cell death in FR overexpressing cancer cells." (PMID 34356120, 2021). "The hypomethylating agent 5-aza-2′-deoxycytidine can influence the differentiation status of cultured cancer cells and inhibit the High Mobility Group AT-Hook Protein 2 (HMGA2)-induced EMT." (PMID 33803458, 2021). "It was reported that HMGA2 is aberrantly regulated malignant signaling in different types of cancers." (PMID 34680349, 2021). "In CRC, m6A reader YTHDC1 expedited cytoplasmic export of circNSUN2 to promote cancer liver metastasis via stabilizing HMGA2, which acted as a driver of cancer metastasis via enhancing EMT process." (PMID 34745970, 2021). "HMGA2 directly binds to the SOX2 promotor and regulates the expression of this gene, which encodes an important cancer stem cell marker." (PMID 33668453, 2021). "HMGA2 increases cancer cell proliferation by promoting cell cycle entry and inhibition of apoptosis." (PMID 33668453, 2021). "Herein, we applied the MTX functionalized G4 dendrimer nanosystem G4/MTX to deliver HMGA2 siRNA into MCF-7 and MDA-MB-231 cancer cells, and studied the effect caused via HMGA2 silencing on the mentioned cells." (PMID 34356120, 2021). "In this study, we aim to reveal the role of HMGA2 in TNBC biology and demonstrate a link between HMGA2-mediated cancer phenotypes and the regulation of NF-kB/IL-6/STAT3 signaling." (PMID 34680349, 2021). "Expression of HMGA2 has been investigated in many cancers including OSCC in tissue biopsies however its expression in liquid biopsy needs to be explored." (PMID 33639654, 2021). "HMGA2 overexpression is thought to be a feature of cancer, and increases in HMGA2 expression are used to predict the efficacy of some cancer chemotherapies." (PMID 34072941, 2021). "In our study, we also investigated the anti-cancer effect of SR-4835 at low concentration on high HMGA2 expression GC, and the results showed the excellent anti-cancer effect, especially when combined with HMGA2 knockout." (PMID 34513922, 2021). "As expected, our prepared nanocomplex selectively accumulated in the cytoplasm of FR expressing cancer cells and indicated high HMGA2 gene silencing efficiency, which finally improved the induction of cell apoptosis." (PMID 34356120, 2021). "High mobility group A 2 (HMGA2) protein is widely expressed in undifferentiated cells including cancer cells." (PMID 34680349, 2021). "To explore the role of HMGA2 in CC, we detected the expression of HMGA2 in CC tissues and cervix tissues with qRT-PCR and western blotting, the results showed that the mRNA and protein levels of HMGA2 were remarkably higher in cancer tissues." (PMID 34336701, 2021). "A physical interaction between human AP endonuclease 1 (APE1) and HMGA2 in cancer cells was demonstrated, which supports the involvement of HMGA2 in the base excision repair (BER) machinery." (PMID 33668453, 2021). "HMGA2 has been reported to enhance cancer progression and drug resistance in several cancers, which eventually leads to poor prognosis." (PMID 33762953, 2021). "In agreement, other studies have reported that HMGA2 increases cancer cell proliferation in different cancer types." (PMID 34680349, 2021). "Specifically, increased expression of GPC3, DLK1, and HMGA2 are genes that define the driving pathways of HB, and these genes have also been previously reported as cancer stem cell markers in HB7,38." (PMID 34497364, 2021). "HMGA2 has been found to promote drug resistance by inherent intrinsic resistance and by inducing cancer stem cell populations." (PMID 33668453, 2021). "HMGA2 is considered to play a key role in the regulation of in cancer cell proliferation, apoptosis, migration, and invasion." (PMID 33519932, 2021).
cancer (continued). "Together, these results confirmed that circFAM73A promotes cancer stem cell-like properties and cell malignancy in GC cells by upregulating HMGA2 expression." (PMID 33731207, 2021). "Studies have shown that HMGA2 increases cancer progression through the activation of several pathways." (PMID 33668453, 2021). "HMGA2 influences the expressions of a broad spectrum of genes, many of which are involved in cancer cell proliferation and survival." (PMID 33668453, 2021). "Coincidentally, transfection of miR-194-5p in the HMGA2-overexpressed cancer cells partially enhanced the colony formation ability, and colonies of the miR-194-5p transfected group were significantly larger than that of the control." (PMID 32228703, 2020). "It was demonstrated that overexpression of the HMGA2 protein occurs in various types of cancer, including CRC." (PMID 32842685, 2020). "Multiple studies have shown that overexpression of HMGA2 affected malignant features in multiple types of cancer." (PMID 32899691, 2020). "For instance, some years ago, down-regulation of a subset of miRNAs that target HMGA1 and HMGA2 (proteins overexpressed in malignant neoplasms) were identified in PitNETs." (PMID 32316225, 2020). "Among the differentially expressed genes, we found that several genes related to cancer progression (HMGA2, PLD2, MMP9, GLI1, GLI2, SLUG and MDR1) were expressed at a low level after knocking out APN." (PMID 32457292, 2020). "Taken together, the miR-212-3p exerts a cancer suppressor role in OS partially by inhibiting its target gene HMGA2." (PMID 32883329, 2020). "Of these, HMGA2 was reported participating in the proliferation of many cancer types, and MMP7 was found affecting the apoptotic process mediated by FAS/FASL system as well as N-cadherin." (PMID 32874135, 2020). "HMGA2 also protects cancer cells from apoptosis by hyperactivating the PI3K/Akt pathway, which impairs the activation of caspase-9 and Bad in a gastric cancer cell line." (PMID 32365712, 2020). "Expression of several genes known to be involved in cancer progression were identified by this method, including HMGA2, FHL1, SLC2A3, ADAMTS1, UPP1, and TGM2." (PMID 32054828, 2020). "Unexpectedly, it was reported that HMGA2, an oncogene with pro-cancer stemness ability, interacted with miR-194." (PMID 32228703, 2020). "ChIP experiments using cancer cells overexpressing HMGA2 showed that HMGA2 prefers binding to AT-rich DNA sequences, although the center sequences are not necessarily GC-rich." (PMID 32466162, 2020). "To validate our results, we utilized cell viability assays and found that expression of HMGA2 correlated with increased cell survival during Etop treatment in all four cancer cell models." (PMID 31271486, 2019). "However, it remains unclear whether HMGA2 regulates angiogenesis-associated genes in cancer cells." (PMID 31109142, 2019). "In this sense, HMGA family members (HMGA1 and HMGA2) comprise an important group of genes involved in cancer genesis and progression." (PMID 31737655, 2019). "We found that the chemosensitivity of cancer cells to the clinically important TOP1 poison irinotecan/SN38 can be determined by the expression level of the oncofetal replication fork chaperone HMGA2." (PMID 31067275, 2019). "A similar role was found for the transcriptional modulator High Mobility Group AT-Hook 2 (HMGA2), which is involved in motility and self-renewal of normal and cancer cells." (PMID 30909628, 2019). "The overexpression of HMGA2 is also correlated with the occurrence of metastasis and poor prognosis in several types of cancers." (PMID 31109142, 2019). "Aberrant overexpression of high mobility group AT-hook 2 (HMGA2) is frequently found in cancers and HMGA2 has been considered an anticancer therapeutic target." (PMID 31581665, 2019).
cancer (continued). "Intriguingly, depending on the relative HMGA2 expression levels in various cancer cell models, HMGA2 either triggered or attenuated the genotoxic action of the clinically important TOP1 poison irinotecan/SN38, specifically at heterochromatic subtelomeres." (PMID 31271486, 2019). "HMGA2 is expressed during early developmental stages and is aberrantly re-activated in many cancers." (PMID 31067275, 2019). "In cancer cells expressing HMGA2, we propose that the protein mitigates the effects of both TOP2 targeting drugs by a combination of DNA supercoil constrainment and TOP2A catalytic activation, hence acting as a DNA supercoil ‘sink’." (PMID 31271486, 2019). "Here, we show that the expression of HMGA2 confers broad protection to cancer cells treated with the clinically important TOP2‐targeting drugs Etop and Merb, leading to a significant reduction in genotoxic DSBs during the course of drug treatment." (PMID 31271486, 2019). "HMGA2 proteins are abundant during embryogenesis and in many malignant neoplasms, such as myeloproliferative neoplasms and pancreatic, thyroid and ovarian cancer." (PMID 31053152, 2019). "The accumulated evidence indicates that high HMGA2 expression is the preferred therapeutic target for any cancer type." (PMID 31684108, 2019). "Collectively, these data led to a new model in which HMGA2 plays an important role in cancer genome stability at topologically challenged chromatin regions, such as replication forks and subtelomeres." (PMID 31271486, 2019). "There have been strong evidences shown that HMGA2 is an important trigger of apoptosis in cancer research." (PMID 30934671, 2019). "Collectively, our data thus argue that the observed differential chemosensitivity of cancer cells to SN38 is caused, at least in part, by the extent of intracellular TOP1cc formation, which is modulated by HMGA2 within ternary scDNA complexes." (PMID 31067275, 2019). "In the previous study, we utilized two HT1080 clonal human cancer cell lines and human embryonic stem cells (hESCs) that permitted us to control endogenous HMGA2 expression levels via sh and si RNA, respectively." (PMID 31067275, 2019). "HMGA2 is frequently overexpressed in cancers and is considered a potential therapeutic target for drug development." (PMID 31581665, 2019). "In this sense, HMGA family members (HMGA1 and HMGA2) comprise an important group of genes involved in the genesis and progression of malignant tumors." (PMID 31737655, 2019). "In our cancer cell models, we observed that high cellular HMGA2 protein levels required higher concentrations of the PARP inhibitor olaparib to block DNA damage‐induced PARP1 activity." (PMID 30289618, 2019). "We demonstrated increased survival of HMGA2 expressing cancer cells under DNA stress, despite the fact that increased PARP1 activity can potentially cause cell death through NAD+ depletion and energy failure." (PMID 30289618, 2019). "We found that the expression of HMGA2 always reduced the occurrence of DSBs that generated the drug‐induced 30–100 kb DNA fragments across all four cancer cell model systems." (PMID 31271486, 2019). "During the proliferation of highly replicating cells as ESCs or cancer cells, HMGA2 expression is irrelevant, however, when forks are arrested; HMGA2 binds with high affinity to branched DNA, stabilizing stalled forks and preventing DNA mutations." (PMID 31428613, 2019). "We now further demonstrate that high levels of HMGA2 also protected cancer cells against DNA breaks triggered by the clinically important TOP1 poison irinotecan." (PMID 31067275, 2019). "To investigate the contribution of HMGA2 to metastasis, we focused on angiogenesis, which plays an essential role in the metastasis of various cancers." (PMID 31109142, 2019). "While low to moderate levels sensitized cancer cells and potentiated the formation of genotoxic TOP1cc, high HMGA2 expression levels protected cells against SN38, at least in part by mitigating TOP1cc formation." (PMID 31067275, 2019).